IL6 (interleukin 6)
Diseases named in the same sentence as IL6 in open-access papers (continued):
Sharing a sentence is not in itself a finding about the gene and the disease.
periodontitis (continued). "Although we cannot confirm, the occurrence of periodontitis could putatively be involved in the negative correlation between IL-6 and PMP in the non-diabetic group, which led to this unexpected association between these molecules." (PMID 39253540, 2024). "Moreover, a bi-directional relationship is suggested by several authors because of the increased production of pro-inflammatory cytokines such as IL1B, IL4, IL6, IL10, CBL, and RELA, which are often present in the periodontitis development and CRC carcinogenesis." (PMID 39517401, 2024). "Inflammatory mediators such as C-reactive protein (CRP), interleukin-6 (IL-6), and tumor necrosis factor-alpha (TNF-α) are elevated in both periodontitis and metabolic syndrome, suggesting a bidirectional relationship where each condition may exacerbate the other." (PMID 39338063, 2024). "The levels of MMP-8 and IL-6 in GCF have shown significant potential to identify individuals with periodontitis and reflect its severity, exhibiting ROC values of 0.92 and 0.93 for MMP-8 and IL-6, respectively, distinguishing between healthy and periodontitis patients." (PMID 38802345, 2024). "However, compared to controls and non-periodontitis patients, salivary IL-6 levels were considerably higher in individuals with periodontitis, suggesting local inflammation." (PMID 39063437, 2024). "MiR-200c directly targets 3′ UTRs of IL-6, IL-8, interferon-related developmental regulator 1 (Ifrd1), and chemokine (C-C motif) ligand 5 (CCL-5), and downregulated their expression in human periodontal ligament, gingival fibroblasts, and the periodontium of periodontitis rats." (PMID 37525201, 2023). "IL17 also induces an increase in osteoclasts not only by stimulating the secretion of IL6 and RANKL, but also by altering the microbial composition of the oral cavity, increasing levels of Enterobacteriaceae, Enterococcus and Staphylococcus, which can aggravate periodontitis." (PMID 36793899, 2023). "From there, the inflammatory response during periodontitis has been shown to be marked by the local release of specific proinflammatory mediators and enzymes, including C-reactive protein (CRP); metalloproteinases (MMPs); interleukin- (IL-) 1β, IL-6, and IL-10; and tumor necrosis factor (TNF-α)." (PMID 37214190, 2023). "Among them, the genus Lachnospiraceae UCG-008 is positively correlated to the release of inflammatory factors such as IL-6, HS-CRP, and TNF-α, indicating that reducing the numbers of Lachnospiraceae UCG-008 is beneficial for controlling inflammation and can function in controlling periodontitis." (PMID 37305424, 2023). "Additionally, EXO-NET EVs from periodontitis patients contained higher amounts of IL-6 and IL-8, and decreased IL-10, compared to those from non-periodontitis patients." (PMID 39697803, 2023). "Moreover, although IL-6 always responded to consistent detectable baseline levels, LL-37 was practically absent in healthy and periodontitis patients after SRP therapy, appearing only in the untreated periodontitis patients." (PMID 37246231, 2023). "IL-6 levels in GCF (pg/site) were elevated for both Stage I-II (590.30 (93.86) pg) and III-IV (759.20 ± (318.00) pg) groups as compared to the healthy group (513.90 (223.70) pg) at baseline, although statistically significant differences were only found for Stage III-IV periodontitis (p < 0.01)." (PMID 37246231, 2023). "In addition, microbiomes from patients with periodontitis increased IL-6 and MMP8 secretion in 25 mM glucose but not in 5 mM glucose." (PMID 37240180, 2023). "Unlike IL-6, IL-1β does not present similar levels in peri-implantitis and in periodontitis." (PMID 37232785, 2023). "In an in vivo study on non-human primates, IL-6 expression was increased during the early phase of periodontitis development, whereas the expression remained low during the progression of periodontitis and during the resolution period after the elimination of inflammation." (PMID 35628348, 2022).
periodontitis (continued). "Therefore, in order to confirm the evidence for the inhibition of inflammatory infiltration, the production of the representative proinflammatory cytokines IL-6, IL-1, and TNF of periodontitis in serum isolated from the blood of periodontitis-induced rats was evaluated." (PMID 36145616, 2022). "The exploratory hypothesis was that pre-pregnancy BMI would be independently associated with changes during pregnancy and early postpartum in inflammatory markers (CRP, IL-6, and MMP-9) and anti-inflammatory cytokine (IL-10) concentrations in pregnant women with periodontitis." (PMID 35270396, 2022). "Similarly, TGF-β not only controls T cell differentiation into regulatory and effector subsets, which is important for the growth and maintenance of immune cells, but it also promotes the production of IL-1, IL-6, as well as TGF-β via inflammatory cells, which helps to the onset of periodontitis." (PMID 36710972, 2022). "In line with this, PBMCs from patients with periodontitis stimulated in vitro with LPS of Escherichia coli, have also demonstrated a proinflammatory secretory pattern with higher levels of the cytokine’s TNF-α and IL-6, among others, in comparison with PBMCs from healthy individuals." (PMID 35300329, 2022). "Moreover, Machado and colleagues showed significantly higher TNF-α and IL-6 levels among pregnant women with periodontitis compared to healthy non-pregnant controls." (PMID 36432584, 2022). "In addition, chronic stress was also related to delayed wound healing in periodontal and peri-implant soft tissues, secondary to reduced levels of IL-1alfa and beta, IL-6, IL-8 and TNF-alfa, as well as hard tissues, thus favoring periodontitis progression and poor osseointegration." (PMID 35323251, 2022). "In a study evaluating periodontitis, Cyanobacteria was demonstrated to modulate a pro-inflammatory response in the oral mucosa through a complex interaction of lipopolysaccharide (LPS)-mediated Toll-Like Receptor 4 (TLR4) blockade, IL-6 production, and miRNA expression." (PMID 36360258, 2022). "The present study aimed to evaluate 3 biomarkers (i.e., IL-1β, IL-6, and MMP-8) out of the 5 most promising salivary host-derived biomarkers identified by recent systematic reviews and meta-analyses as good candidates to be chosen for the early diagnosis of periodontitis." (PMID 35368315, 2022). "Pro-inflammatory cytokines, such as tumor necrosis factor (TNF-α) and interlukin (IL-6) directly, and indirectly activated osteoclast differentiation through receptor activator of nuclear factor-κB ligand (RANKL)/RANK pathway and induced alveolar bone resorption in periodontitis." (PMID 33498415, 2021). "Furthermore, animal studies have provided some evidence to show that miR-146a exerts anti-inflammatory impacts in periodontitis through inhibiting the expressions of the pro-inflammatory cytokines such as tumor necrosis factor-alpha (TNF-α), interleukin-1β (IL-1β), and IL-6 in periodontal tissue." (PMID 34645448, 2021). "Unlike those from healthy individuals, OBMC-derived supernatants from periodontitis patients exhibited decreased ability to induce secretion of IFN-γ by allogeneic healthy PBMCs treated with IL-2, while they triggered significant levels of TNF-α, IL-1β and IL-6 by untreated PBMCs." (PMID 33672708, 2021). "Serum reactive oxygen species, interleukin (IL)-1, IL-6, tumor necrosis factor (TNF)-α, and CRP have been found to be elevated in the bloodstream of patients with established T2DM and may play an important role in tissue breakdown in periodontitis." (PMID 33924022, 2021). "Besides, the existence of elevated cytokines expression comprising pro‐inflammatory and regulatory cytokines such as IL‐1β, interferon (IFN)‐γ, IL‐1 receptor antagonist (RA), IL‐4, IL‐6, IL‐10, IL‐12, TNF‐α, and induced protein (IP)‐10, lead the way to periodontitis’ inflammatory process." (PMID 34272761, 2021).
periodontitis (continued). "In obese subjects with periodontitis, pro-inflammatory cytokines (Interleukin-1β (Il-1β), Interleukin-6 (Il-6), Tumor Necrosis Factor α (TNF-α)) were found in greater quantities in the blood and also in the crevicular gingival fluid compared to normo-weighted subjects with periodontitis." (PMID 33919425, 2021). "Today, predominant opinion connects the local inflammation of periodontitis with chronic systemic inflammatory diseases via mediating pathways characterized by various indicators of inflammation such as fibrinogen, C-reactive protein (CRP), and interleukin IL-6." (PMID 32827080, 2021). "In the other part, periodontitis, through bacteria or their virulence factor translocation, act like a constant challenge to immune inflammatory cells, increasing the release of pro-inflammatory mediators (CRP, TNF-α, IL-6, and IL-1β) and periodontal-derived EVs into circulation." (PMID 34769262, 2021). "Pro-inflammatory cytokines, such as IL-1β, IL-6, and TNF-α, are representative co-related molecules involved in the induction and regulation of the inflammatory cascade in systemic inflammatory disorders, including RA, periodontitis, and gut inflammatory diseases." (PMID 33716675, 2021). "In addition, PGFE effectively regulated the expression of the pro-inflammatory cytokines IL-6, IL-1β, and TNF-α, which play an important role in the regulation of periodontitis in PG-LPS-stimulated HPDL cells, and it effectively suppressed the mRNA levels of these pro-inflammatory cytokines." (PMID 33287198, 2020). "Furthermore, the level of IL-6 in GCF samples of type 2 diabetes mellitus patients with periodontitis was significantly higher than in systemically-healthy people with or without periodontitis." (PMID 33081038, 2020). "Likewise, three studies, including 254 patients, reported IL-6 serum levels of transplanted with and without periodontitis." (PMID 32230707, 2020). "The overall result suggests a slightly increased value of serum IL-6 levels in transplanted patients with periodontitis when compared to transplant recipients without periodontitis, with an average of 2.20 pg/mL above (p < 0.01) (MD (95% CI): 2.20 (1.00–3.39))." (PMID 32230707, 2020). "In addition, one of the most important key factors responsible for periodontal destruction is the upregulation of inflammatory cytokines, including IL-1β, IL-6, and TNF-α, in the inflammatory sites of periodontal tissue; these cytokines are mainly involved in the pathogenesis of periodontitis." (PMID 33287198, 2020). "In our study, we focused on the expression of three proteins, IL-6, CXCL8, and CCL2, which are thought to play an essential role in periodontal tissue inflammation and are usually regarded as the factors which enhance the inflammatory response in periodontitis." (PMID 31178663, 2019). "However, there is no information regarding the ratio of inflammatory markers (IL-6/IL-10) in different genotype distribution of IL-10 gene in chronic periodontitis." (PMID 29489938, 2018). "Taken together we propose that selective targeting of the IL-6 signaling pathway, rather than gingipain inhibition, might have a potential therapeutic value in treatment of periodontitis." (PMID 28497028, 2017). "Taken together, the inhibition of IL-6 signaling rather than gingipain activity might be a more appropriate target of treatment of chronic periodontitis since it leads to restoration of the low level of Th17 and regulation of its biological activity." (PMID 28497028, 2017). "Therefore, the aim of the present study is to compare periodontal parameter values and serum levels of IL‐6, sIL‐6R, soluble gp130 (sgp130), serum amyloid A (SAA), TNF‐α, IL‐17, and total immunoglobulin G (IgG) in patients with RA and periodontitis before and after TCZ therapy." (PMID 29744142, 2015).
periodontitis (continued). "Based upon the increased expression of IL-1 and IL-6 in inflamed gingiva and high levels of GCF in periodontitis patients, several studies have suggested that an increased production of these cytokines may play an important role in periodontal tissue destruction." (PMID 25888355, 2015). "Consistent with previous studies, our results demonstrate that LPS upregulates IL-1, IL-6, and TNF-α gene expression in hPDLCs, whereas pretreatment with PTL effectively inhibits the production of these cytokines, thus indicating the anti-inflammatory potential of PTL in treatment of periodontitis." (PMID 25610476, 2014). "Thus, considering all the GCF samples (from periodontitis patients and controls), the percentage of samples considered below the detection level were 13% for IL-1β, 31% for IL-6, 3% for IL-10 and 5% for TNF-α (data not shown)." (PMID 24944641, 2014). "RANKL stimulates bone resorption and is upregulated by IL-1β and IL-6 among other cytokines; thus the ratio of RANKL and its natural antagonist osteoprotegerin (OPG) is a particularly important factor in determining bone cell resorption and turnover and this ratio is elevated in periodontitis." (PMID 24944840, 2014). "On the other hand the factors (selection criteria, ethnicity) along with the severity of the disease may partially explain why we were not able to find any association of periodontitis with other SNPs such as INF-γ, IL-1β, IL-6." (PMID 24274085, 2013). "The aftermath of inflammatory progression of periodontitis systemically leads to production of mediators in the vicinity such as C-reactive protein (CRP), interleukins-1beta (IL-1β), tumor necrosis factor-alpha (TNF-α) and interleukin 6 (IL-6) i.e Proinflammatory cytokines." (PMID 24198887, 2013). "Additionally, IL-6 was not evaluated, which could have provided a more comprehensive view of the systemic inflammatory impact of periodontitis." (PMID 40451975, 2025). "Besides, systemic inflammatory biomarkers such as C-reactive protein (CRP) and IL-6 may not fully reflected the local periodontal inflammation, resulting in the inability of DII to sensitive feedback the risk of periodontitis." (PMID 40612309, 2025). "Similarly, another study in patients with malocclusion secondary to periodontitis, used traditional straight-wire orthodontic treatment and invisible orthodontic treatment without brackets for therapy and found reduced levels of IL-6 in gingival crevicular fluid and serum after 6 months of therapy." (PMID 39253090, 2024). "PGE2 can enhance the synthesis of IL6, a pro-inflammatory cytokine, which, if not properly controlled, may result in chronic inflammation and the progression of many inflammatory diseases, including various oral entities, i.e., periodontitis." (PMID 39769290, 2024). "CD14+ monocytes secrete a variety of cytokines, including TNF-α, IL-1β, IL-6, IL-8, CCL2, CCL3, and CCL5, compared to CD14− cells from GCF in patients with periodontitis, which suggests that CD14+ monocytes may be a source of CCL5 in GCF and gingival tissue in patients with periodontitis." (PMID 38139161, 2023). "Although IL-6 could be detected in inflamed gingiva tissues and in manifest periodontitis tissue by ELISA in a previous study we could not detect any differences in IL-6 expression between healthy controls and IBD patients, even though the cytokine was detectable in all groups." (PMID 34383142, 2022). "Of particular interest, in periodontitis patients, IL-36γ mRNA is positively correlated with archetypal inflammatory cytokines already known to be involved in periodontitis and inflammatory diseases, i.e., IL-1β, IL-6, TNF-α and IL-17A while IL-36β or IL-36Ra are not correlated with these cytokines." (PMID 31848404, 2019).
periodontitis (continued). "A possible explanation of the high proportion of CRP levels in patients with periodontitis compared to healthy controls could be due to the strong impact exerted by periodontopathogenic bacteria on systemic inflammation mediated by a CRP pathway, mainly measured by CRP and interleukin 6 (IL-6)." (PMID 31817862, 2019). "According to these reports, IL-6 may not be used as a biomarker for the diagnosis of periodontitis." (PMID 25884025, 2015). "However, the role of IL-6 in the etiology of periodontal disease remains unclear and its role in the resorption of alveolar bone coincident to periodontitis has not been specifically determined." (PMID 20407653, 2009). "Given these considerations, this study aimed to assess and establish links between periodontal health and blood levels of IL-6, LDH, and CRP among second-trimester pregnant women, regardless of their chronic periodontitis status." (PMID 38595889, 2024). "The objective of this study was to compare the periodontal health and blood levels of IL-6, LDH, and CRP in pregnant women with and without chronic periodontitis." (PMID 38595889, 2024). "Specifically, combinations such as MMP-8 with IL-1β, IL-1β with IL-6, or MMP-8 with IL-6 correctly identified 78%–81% of patients with periodontitis and excluded 85%–88% of non-periodontitis participants." (PMID 39554809, 2024). "In a recent study of the oral cavity of SSc patients, the expression of MMP-9 and CXCL4, but not IL-6, in the GCF correlated with early-stage SSc and several parameters of periodontitis." (PMID 38779873, 2024). "We did not detect higher LPS or sCD14 levels as markers of bacterial translocation in PLWH with severe periodontitis, nor did we detect an elevation of systemic IL-6, sCD163, CXCL10 as markers of inflammation in PLWH with severe periodontitis." (PMID 36316604, 2023). "TNF-α enhances the expression of IL-1β, IL-6, and RANKL; however, its level in the gingival crevicular fluid (GCF) does not considerably differ before and after periodontitis treatment." (PMID 38002398, 2023). "Our finding of a high concentration of IL-6 in GCF from patients with OSA and periodontitis has not been reported before in literature." (PMID 36967976, 2023). "Unlike antimicrobial peptide LL-37 and IL-6, IL-4 and IL-10 levels in GCF were substantially lower in the periodontitis groups as compared to healthy individuals at baseline." (PMID 37246231, 2023). "The results of the current study showed that the CAD with moderate–severe periodontitis group presented a higher level of IL-6 and CRP in comparison with the mild periodontitis group; however, our results were not statistically significant." (PMID 37239434, 2023). "As such, the expression of these cytokines can increase with non-cancer-associated inflammatory conditions, such as periodontal disease; although, it was reported that salivary levels of IL6 and IL8 in OSCC were not influenced by chronic periodontitis." (PMID 36900301, 2023). "These diseases lead to an increase in the salivary IL-6 and TNF-α levels of pregnant women compared with pregnant women without gingivitis and periodontitis." (PMID 35877392, 2022). "Patients with chronic periodontitis have elevated levels of proinflammatory mediators, including TNF-α, IL-1, and IL-6 in gingival crevicular fluid, even in the absence of other chronic systemic diseases." (PMID 34043630, 2021). "The present study aimed to investigate YKL-40 and IL-6 levels in saliva and gingival crevicular fluid (GCF) of patients with chronic periodontitis (CP) after non-surgical periodontal therapy for the first time." (PMID 32895666, 2020). "This study evaluated the gene expression of IL-1ß, IL-6, TNF-α, MMP-1, MMP-2, MMP-8, MMP-9, TIMP-1, and TIMP-2 in the gingival tissue of individuals with periodontitis or peri-implantitis compared to individuals without periodontal or peri-implant disease." (PMID 33291232, 2020).